GLI1 (GLI family zinc finger 1)
Description:
Transcription activator that acts as a key effector of the smoothened signaling pathway, and which plays a role in craniofacial development and digital development, as well as development of the central nervous system and gastrointestinal tract. Binds to the DNA consensus sequence 5'-GACCACCCA-3'. Activated in response to smoothened signaling: in presence of hedgehog (DHH, IHH or SHH) and subsequent activation of smoothened, GLI1 translocates to the nucleus and promotes expression of target genes. In contrast to GLI2 and GLI3, does not contain a repressor domain and only acts as a transcription activator. [Isoform 2]: Acts as a transcriptional activator, but activates a different set of genes than isoform 1. Activates expression of CD24, unlike isoform 1.
Synonyms: GLI; PAPA8; PPD1
Tractability: Small molecule: a high-quality ligand is known. Antibody: its Gene Ontology location is reachable by antibodies, with high confidence. PROTAC: UniProt records ubiquitination sites on it; ubiquitination databases record sites on it; a small molecule that binds it is known.
Target class: Transcription factor
Chemical probes: ML340
Gene: Protein-coding gene on chromosome 12 (57,459,785 to 57,472,268, forward strand). Ensembl gene ENSG00000111087.
Subcellular location: Cytoplasm; Nucleus; Cell projection, cilium; Cytoplasm (Isoform 2)
Subcellular location (Human Protein Atlas): Nucleoplasm; Basal body; Cytosol; Primary cilium tip
Pathways (Reactome):
Signal Transduction: Degradation of GLI1 by the proteasome; GLI proteins bind promoters of Hh responsive genes to promote transcription; Hedgehog 'off' state; Hedgehog 'on' state
Gene Ontology:
Molecular function: DNA binding; DNA-binding transcription activator activity, RNA polymerase II-specific; protein binding; RNA polymerase II transcription regulatory region sequence-specific DNA binding; sequence-specific DNA binding; transcription cis-regulatory region binding; DNA-binding transcription factor activity, RNA polymerase II-specific; RNA polymerase II cis-regulatory region sequence-specific DNA binding; chromatin binding; double-stranded DNA binding; microtubule binding
Biological process: epidermal cell differentiation; negative regulation of canonical Wnt signaling pathway; osteoblast differentiation; positive regulation of cardiac muscle cell proliferation; positive regulation of cell cycle G1/S phase transition; positive regulation of cell population proliferation; positive regulation of DNA replication; positive regulation of DNA-templated transcription; positive regulation of transcription by RNA polymerase II; regulation of DNA-templated transcription; smoothened signaling pathway; digestive tract morphogenesis; regulation of smoothened signaling pathway; regulation of transcription by RNA polymerase II; anatomical structure morphogenesis; liver regeneration; prostate gland development; regulation of gene expression; regulation of osteoblast differentiation; spermatid development
Cellular component: ciliary basal body; ciliary tip; cytoplasm; cytosol; GLI-SUFU complex; nucleoplasm; nucleus; ciliary base; axoneme; cilium; non-motile cilium
Genetic constraint (gnomAD): Loss-of-function variants: 47 observed, 85.19 expected, observed/expected ratio (o/e) 0.55, 90% interval 0.44 to 0.7. The upper end of that interval is the gene's LOEUF score, 0.7, which puts it in group 2 of 6, group 1 being the genes least tolerant of losing a copy. Missense variants: 1,268 observed, 1,451.4 expected, observed/expected ratio (o/e) 0.87, 90% interval 0.83 to 0.92. Synonymous variants: 520 observed, 566.87 expected, observed/expected ratio (o/e) 0.92, 90% interval 0.85 to 0.99.
Homologues: Orthologues: chimpanzee GLI1 (99% identical), macaque GLI1 (97% identical), pig GLI1 (91% identical), dog GLI1 (91% identical), guinea pig GLI1 (89% identical), rabbit GLI1 (88% identical), mouse Gli1 (86% identical), rat Gli1 (86% identical), zebrafish gli1 (45% identical), tropical clawed frog gli1 (45% identical). Paralogues in human: GLI2 (38% identical), GLI3 (36% identical), GLIS3 (17% identical), GLIS1 (14% identical), GLIS2 (13% identical), ZIC2 (12% identical), ZIC1 (11% identical), ZIC3 (11% identical), ZIC5 (11% identical), ZXDC (11% identical), ZXDA (10% identical), ZXDB (10% identical), and 2 more.
Diseases named in the same sentence as GLI1 in open-access papers:
GLI1 is named in the same sentence as 346 diseases in open-access papers, as found by Europe PMC text mining. Sharing a sentence is not in itself a finding about the gene and the disease. The quoted sentences say what the papers report.
breast carcinoma (150 papers, 2009 to 2025). "Among the integrin family, integrin α6 is known to promote the self-renewal ability of breast cancer cells through focal adhesion kinase (FAK) signaling linked to the expression of the Hedgehog effector GLI-1 and a key stem cell factor BMI-1." (PMID 38664825, 2024). "We performed hierarchical clustering of ROR1 with 24 EMT-related genes including the Hippo signaling pathway genes from the MSigDB database along with WNT5a, BMI1, BCL2, and GLI1 prompted by associations noted in prior studies on breast cancer or CLL." (PMID 37029329, 2023). "Further, silencing OPN or GLI1 improved the susceptibility of breast cancer cells to all three cytotoxic chemotherapeutics." (PMID 36672705, 2023). "This study aimed to evaluate the expression of sonic hedgehog (SHH) and glioma-associated oncogene 1 (GLI-1) in the serum and mammary tumour tissues of dogs." (PMID 37932728, 2023). "According to the results, GLI1 gene was the most frequently associated gene with the poor prognostic features of breast cancer patients including late stage (p = 0.0001), node positive (p = 0.044), and metastasis (p = 0.022)." (PMID 34722544, 2021). "In fact, the truncated GLI1 (tGLI1) splice variant presents a unique opportunity to validate a novel actionable target for gliomas and breast cancer brain metastases due to its tumor-specific expression and potent oncogenic effects." (PMID 32957513, 2020). "We have reported that Gli1 is associated with stemness in breast cancer and lung squamous cell carcinoma." (PMID 32430068, 2020). "This is supported by findings that SHH, PTCH1, and GLI1 mutations are exceedingly rare in breast cancer which argues against the potential involvement of mutational activation of the SHH pathway in breast cancer." (PMID 32957513, 2020). "In breast cancer cells, Vegfa mRNA expression is shown to be specifically activated by a truncated form of Gli1 (splicing variant), while full-length Gli1 seems unable to bind Vegfa promoter and to activate its transcription." (PMID 31238510, 2019). "Increased GLI1 expression in breast cancer is associated with aggressive tumor behavior, resulting in higher tumor staging and lymph node status." (PMID 31898580, 2019). "Gain of chromosomal region 12q13.2–q13.3 which surrounds GLI1 genomic locus has been linked to breast cancer development." (PMID 30158435, 2018). "This was observed in pancreatic carcinoma, while decreased GLI1 expression caused by inhibition of NFKB was observed in breast cancer." (PMID 30158435, 2018). "tGLI1 is an alternatively spliced, shorter variant of GLI1, and its expression is induced in glioblastomas and breast cancer." (PMID 29695137, 2018). "In this direction is also the protective role of FOXS1 expression in relapse‐free survival of breast cancer, another tumor where GLI1 signaling has been implicated." (PMID 30098229, 2018). "Elevated Gli-1 and Gli-2 protein level in human breast cancer was associated with poor prognosis and progressive stages of disease." (PMID 29734730, 2018). "In breast cancer GLI1 is upregulated due to the loss of lysine methyltransferases (KMT) SETD7 which can put repressive marks on histones within GLI1 promoter and loss of these marks results in GLI1 overexpression." (PMID 30158435, 2018). "Consistently, there was also significant association between Gli1 over-expression and poor OS (HR = 2.05, 95% CI: [1.60, 2.64]) of breast cancer patients." (PMID 29113369, 2017). "Nuclear GLI1 overexpression in breast cancer has been associated with increased invasiveness, early relapse after radical operation, and metastasis." (PMID 27548161, 2016). "Genetic alternations in components of the HH pathway, including loss of PTCH1 or GLI1 amplification, were suggested to result in breast cancer." (PMID 27689403, 2016). "GLI1 has been implicated in several of these processes in transformed cells and in some breast cancer cell lines." (PMID 25252859, 2014).
breast carcinoma (continued). "We found that negative correlation between LKB1 and glioma-associated oncogene homologue 1 (GLI1) in these three breast cancer cell lines." (PMID 23861764, 2013). "Recent studies have demonstrated that aberrant activation of the Hh cascade in human breast cancer can be caused by elevated levels of Hh ligands, such as GLI1." (PMID 23861764, 2013). "A critical feature of GLI1 in this context is its ability to induce BMI-1, a transcriptional repressor that has been implicated in the function of mammary tumour stem cells." (PMID 23436775, 2013). "In esophageal squamous cell carcinoma, GLI1 expression has been associated with lymphatic metastasis, while in breast cancer, strong nuclear GLI staining was observed." (PMID 22295244, 2012). "Elevated levels of GLI1 protein in human breast cancer are associated with unfavourable prognosis and progressive stages of disease." (PMID 19706168, 2009). "The results from these analyses underlined a potential involvement of GLI1 as a transcriptional regulator important for breast cancer development as increased levels of GLI1 expression were shown in four out of five analysed samples." (PMID 19706168, 2009). "Glioma-associated oncogene 1 (GLI1) is a critical transcriptional factor of the sonic hedgehog pathway that tends to have higher expression in progressive stages and is related to the unfavorable prognosis of breast cancer." (PMID 40426890, 2025). "Additionally, the presence of a recently described GLI1 splicing variant has been associated with increased cell motility and invasiveness in both glioblastoma and breast cancer." (PMID 36765685, 2023). "Hence, GLI1 can be a future diagnostic and prognostic marker as well as a potent therapeutic target in breast cancer." (PMID 36046646, 2022). "Overexpression of GLI1 is closely associated with poor prognosis in breast cancer." (PMID 36046646, 2022). "However, in fully differentiated tissues, GLI1 can act as an oncogene and has been implicated in a wide variety of cancers, including glioblastoma, breast cancer, and colon cancer." (PMID 36712323, 2022). "Furthermore, breast cancer cell line (MDA-MB-231) was used to investigate the probable association of FGFR1 with SHH and GLI1 in breast cancer progression." (PMID 34722544, 2021). "In support of this, complete inhibition of GSK3β with MeBIO caused a significant increase in GLI1 expression, whereas the introduction of constitutively active GSK3β by the transfection of breast cancer cells enhanced drug retention ability that is abrogated by OPN treatment." (PMID 34638233, 2021). "Gli1 has been implicated in several human cancers, including a role in the progression of pancreatic cancer and an association with poor prognosis in glioblastoma, pancreatic cancer, and breast cancer." (PMID 32430068, 2020). "Thus, a meta-analysis was performed to clarify the association of Gli1 over-expression, clinic-pathological characteristics, molecular subtypes and prognosis in breast cancer." (PMID 29113369, 2017). "Hence, to clarify the association of Gli1 over-expression and clinicopathological features, molecular subtypes, and clinical outcomes in breast cancer, a meta-analysis was performed via acquired available published data." (PMID 29113369, 2017). "Interestingly, previous studies in breast cancer have demonstrated that nuclear staining of GLI1 in cancer cells is associated with aggressive tumor characteristics (i.e., tumor stage and lymph node status), early recurrence, and poor prognosis." (PMID 26927093, 2016). "Paracrine Hh signaling has been implicated in stromal‐dependent tumor growth in breast cancer 56, 116 and a paracrine signature of high epithelial Hh ligand and high stromal GLI1 expression was found to be an independent predictor of decreased overall survival." (PMID 27539549, 2016). "Indeed, the expression of GLI1 is also associated with low survival rates of breast cancer patients." (PMID 26413813, 2015).
breast carcinoma (continued). "Activated NFκB and expression of GLI1 have been associated with poor prognosis in breast cancer." (PMID 25252859, 2014). "For example, loss of PC in breast cancers initiated by Gli1 may promote tumor formation whereas tumors initiated by excess Hh ligand, mutations in Ptc1, or activated Smoothened could be inhibited." (PMID 24594320, 2014). "GLI1 expression in mice causes mammary tumors with a basal-like phenotype." (PMID 25252859, 2014). "Furthermore, we also observed negative correlation between LKB1 and glioma-associated oncogene homologue 1 (GLI1) in three breast cancer cell lines." (PMID 23861764, 2013). "To determine how the normal fibroblast differentiation hierarchy changes through oncogenesis, we crossed Pdgfra-GFP or Gli1-GFP reporter mice with the MMTV-Wnt1 model of breast cancer (raGFP-Wnt1 or Gli1-Wnt1, respectively)." (PMID 40216939, 2025). "In breast cancer, the activation of the pathway in CSCs expressing GLI1 or GLI2 through Hh ligands or inhibition of GLI1 or GLI2 using cyclobutrazine or siRNA results in a change in BMI-1 expression." (PMID 40034124, 2025). "The findings of this study will serve to provide valuable evidence regarding the role of GLI1 in breast cancer and its potential as both a prognostic biomarker and a therapeutic target." (PMID 39483334, 2024). "The pivotal roles of integrin α11, and EZH2, which regulates integrin α11 expression along with GLI-1, suggest them as potential targets for inhibiting drug-resistant breast cancer." (PMID 38664825, 2024). "Retinoic acid, a metabolite of retinol, has been shown to regulate GLI1 expression and Hedgehog signaling, which is frequently dysregulated in breast cancer." (PMID 39483334, 2024). "Nevertheless, the immunoinfiltration and tumor microenvironment of GLI1 in breast cancer have been poorly studied." (PMID 39483334, 2024). "Further in-depth mechanistic investigations are necessary, such as employing transwell invasion assays and wound healing assays to explore the impact of GLI1 on cellular behavior within the immune microenvironment of invasive breast cancer." (PMID 39483334, 2024). "GLI1 was upregulated which coincided with loss of mono-methylation at histone 3 lysine 4, while SHH was hypomethylated and overexpressed in breast cancer." (PMID 38474826, 2024). "Termed truncated GLI1 (tGLI1), an alternative splice variant of GLI1, retains the known GLI1 functional domains, and promotes stemness gene expression (Nanog, SOX2, and OCT4) in breast cancer, ultimately leading to metastasis and drug resistance." (PMID 37174034, 2023). "Concurrently, irradiated breast cancer cells display localization of GLI1 to the nucleolus as represented by clear colocalization of GLI1 and nucleolar markers UBF (UBTF) and Fibrillarin (FBL)." (PMID 37380890, 2023). "Other researchers have detected similar percentages of stemness and invasiveness of breast cancer cells in these cell lines, which were modified by estrogen through Gli1 activation." (PMID 38001682, 2023). "Cumulatively, this study establishes a novel role for nucleolar GLI1 in orchestrating recovery of RNA Pol I activity, presenting ribosome biosynthesis and Hh activity as actionable signaling mechanisms in irradiated breast cancer cells." (PMID 37380890, 2023). "Our work establishes a novel role for GLI1 in orchestrating RNA Pol I activity in irradiated breast cancer cells." (PMID 37380890, 2023). "GLI1 activation is one of the mechanisms by which estrogen exposure promotes the proliferation and epithelial-mesenchymal transition of breast cancer stem cells, and GSK3β inactivation can inhibit the activation of GLI1." (PMID 37700593, 2023). "We also observed that the accumulation of lactate significantly increased SHH, SMO, and GLI1 expression of the SHH signaling pathway in breast cancer cells." (PMID 36737428, 2023). "Gli-1 expression is high in breast cancer and contributes to therapeutic resistance in both ER+ and ER− BC cells through Wnt signaling." (PMID 37296983, 2023).